RXRA (retinoid X receptor alpha)
Diseases named in the same sentence as RXRA in open-access papers (continued):
Sharing a sentence is not in itself a finding about the gene and the disease.
hepatoma (32 papers, 2012 to 2025). "In addition to reduced levels of RXRα protein, altered RXRα function by phosphorylation is associated with the development of human hepatocellular carcinoma and colon cancer." (PMID 22545132, 2012). "Though the profile of miRNA was not evaluated in this study, HULC is known to modulate abnormal lipid metabolism in hepatoma cells through an miR9-medicated RXRA signaling pathway." (PMID 32413995, 2020). "HULC promotes tumor angiogenesis in liver cancer through miR-107/E2F1/SPHK1 signaling and modulates abnormal lipid metabolism in hepatoma cells through a miR-9-mediated RXRA signaling pathway." (PMID 28427159, 2017). "Our group reported that the HBx-elevated HULC promoted hepatoma cell proliferation via decreased p18 and increased abnormal lipid metabolism in hepatoma cells through a miRNA-9 mediated RXRA signaling pathway." (PMID 26540633, 2016). "The phosphorylated form of RXRα (p-RXRα) lost its transactivation activity and interfered with the function of the remaining normal RXRα in a dominant-negative manner, thereby promoting the grow of hepatoma cells." (PMID 37566072, 2023). "In relation to other hepatobiliary cancers listed in the Oncomine database, cholangiocarcinoma had the lowest FXR and RXRα RNA expression when compared to the combined hepatocellular carcinoma and cholangiocarcinoma and also the hepatocellular carcinoma cases in the Woo Liver dataset." (PMID 31964941, 2020). "RXRA was found to be up-regulated in hepatocellular carcinoma patients." (PMID 26442469, 2015). "ACR treatments on hepatoma cell lines can suppress growth through inducing of apoptosis via caspase-3 cleavage, inhibiting RXRα phosphorylation by suppressing Ras-MAPK pathway, up-regulating RARβ expression, and promoting cell cycle arrest by increasing cellular levels of p21CIP1." (PMID 24379011, 2013). "Furthermore, a recent study has revealed that PPAR-γ seems to be involved in the epigenetic regulation of miR-122 whose gene transcription is enhanced as a result of increased affinity of PPAR-γ and retinoid X receptor alpha (RXRα) complex to the gene promoter in hepatocellular carcinoma cells." (PMID 26516376, 2015). "A previous study found that miR-27a regulated many lipid metabolism-related transcription factors, including RXRα, PPARγ, FASN, SREBP1, and SREBP2 in human hepatoma cells." (PMID 29445089, 2018). "Other studies showed that peretinoin suppressed cell growth and induced apoptosis in hepatoma cells and a DEN-induced mouse hepatoma model through inactivation of the Ras-ERK signaling system and subsequent RXRα dephosphorylation." (PMID 29208982, 2017). "MIR-27a was described to be involved in lipid metabolism, by regulating RXRα, PPARα/γ, FASN, SREBP1, SREBP2, and was able to inhibit HCV replication in human hepatoma cells." (PMID 26728044, 2016). "Furthermore, TNFα and IL1β treatment of Hep3B human hepatoma cells and mice resulted in decreased expression of RXRα, PPARα, PPARγ, LXRα, as well as their co-activators PGC1α and PGC-1β, which may contribute to the cytokine induced modulations in hepatic energy homeostasis." (PMID 24112857, 2013). "Indeed, our results showed that GSK-3β and RXRα were co-immunoprecipitated mutually in HCC tissues and HepG2 hepatoma cells." (PMID 31938062, 2020). "Interestingly, HNF4G implies a negative regulation by interacting with FOXA1, RXRA, and HNF4A in the human hepatoma cell line and some studies have showed that interrelationships among FOXA1, FOXA2, HNF4A, and HNF4G affect transcriptional regulation." (PMID 29033978, 2017). "Since the PPARα agonist GW7647 increased PDZK1 expression in Huh-7 hepatoma cells, as well as in Caco-2BBE cells, it is possible that the positive effect of RA on PDZK1 expression exerts its effect via binding of RXRα to the PPRE element as well as the RARE element." (PMID 28223944, 2017).
Obesity (31 papers, 2007 to 2025). Accumulation of substantial excess body fat. "Furthermore, to assess the effect of obesity-associated insulin resistance on RXRα S22 phosphorylation in BAT, we measured RXRα S22 phosphorylation in BAT from either lean mice fed with control diet (CD) or diet-induced obese and hyperglycaemic mice fed a high-fat diet (HFD) for 8 weeks." (PMID 32249683, 2020). "For those 12 genes, six of them (DDO, SEPT9, TMEM45B, RXRα, ZNF395 and AHRR) were previously reported to be implicated in the obesity or related diseases and the rest six were novel (PACRG, LINC00494, KLHL4, DTX1, VCX3A and VSTM1)." (PMID 35568907, 2022). "Consistently, selective ablation of RXRα in adipose tissue results in impaired lipolysis during fasting, impaired adipogenesis and resistance to obesity." (PMID 32249683, 2020). "Adipose tissue-specific knockout of RXRα resulted in resistance to diet-induced obesity in mice, owing to impaired adipogenesis and lipolysis." (PMID 32478078, 2020). "We also found that RXRα S22 phosphorylation is promoted by insulin and upon re-feeding in brown adipose tissue in vivo, and that insulin-stimulated S22 phosphorylation of RXRα is dampened by diet-induced obesity." (PMID 32249683, 2020). "An association between increased methylation of the promoter of the RXRA gene in the cord blood of children, and later obesity was seen in 2 cohorts in the UK." (PMID 28898241, 2017). "To date, some RXRα modulators have been reported to exhibit glucose-lowering, insulin-sensitizing or anti-obesity effects." (PMID 22384078, 2012). "The focus of PPARα/RXRα has been mainly its role in obesity and atherosclerosis, however recent data suggests that crosstalk between PPARα and the estrogen receptors exists through competitive binding to the estrogen response elements." (PMID 20799942, 2010). "The epigenetic modulation exerted by breastfeeding seems to also affect other genes involved in energy metabolism, such as fat mass and obesity-associated (FTO) gene, Retinoid X Receptor Alpha (RXRA), and human peroxisome proliferator-activated receptor gamma (PPAR-γ) gene." (PMID 40004988, 2025). "It has been indicated that the methylation status of the retinoid X receptor alpha promoter in umbilical cord tissue might be utilized to identify individual vulnerability to the later obesity and metabolic diseases." (PMID 33663609, 2021). "Besides the roles in the regulation of adipocyte differentiation and obesity, miR-27 family also play important role in inflammatory response and immune response through PPARs and RXRα or NF-κB pathway." (PMID 30778336, 2019). "Despite the fact that AR exerts pro-inflammatory effects like PPARD and RXRA, it was much less associated with development of obesity and diabetes unlike PPARD and RXRA." (PMID 29065888, 2017). "Indeed, members of the nuclear hormone receptor family, including RXRA, have been intensively studied as targets for therapeutic drugs for human diseases such as type II diabetes, obesity, and cancer." (PMID 17705877, 2007). "Carriers of the rs1059491G allele in the sulfotransferase family 1A member 2 (SULT1A2) gene exhibited a 54% reduction in overweight/obesity risk compared to non-carriers, a phenomenon potentially mediated through its location within the PPARγ2 and RXRA transcription factor binding sites." (PMID 41340654, 2025). "Interestingly, insulin-induced RXRα S22 phosphorylation is dampened by diet-induced obesity." (PMID 32249683, 2020). "Taken together, our results revealed (i) a novel RXRα-mediated mechanism by which transcription of the chicken PLIN1 gene is regulated and (ii) the role of RXRα in adipogenesis, which may allow us to identify novel therapeutic strategies to protect against obesity." (PMID 32478078, 2020).
Obesity (continued). "The network shows that RXRA interacts with proteins related to a tumor (THRA related to pituitary adenome) and those related to certain diseases caused by abnormalities in lipid metabolism (e.g., NR0B2 related to obesity, PPARA to hyperapobetalipoproteinemia, and PPARGC1A to lipodystrophy)." (PMID 17705877, 2007). "RXRA also activates the PI3K/AKT pathway, which is known to be involved in the development of obesity and T2DM." (PMID 38339094, 2024). "Therefore, we hypothesized that obesity during pregnancy induces dysregulation in circulating steroid hormones of the obese mothers, disturbing DNA methylation of the RXRα gene and expression of RXRα mRNA and RXRα protein in umbilical cord of the offspring in a sex-dependent manner." (PMID 36072345, 2022). "Using the rat model, we confirmed the presence of heterogeneous RXRα gene methylation near the EGR-1 binding site in the fetus’s umbilical cord, showing that male fetal offspring exposed to maternal obesity had hypermethylation in the RXRα gene near the EGR-1 binding site." (PMID 36072345, 2022). "In addition, the selective deletion of RXRα in adipocytes renders mice resistant to chemical- and high fat diet (HFD)-induced obesity, indicating a role of RXRα in lipogenesis." (PMID 26110391, 2015).
colon carcinoma (27 papers, 2008 to 2026). "Recently, we reported that overexpression of SphK2 correlated to the loss of RARβ and RXRα in colonic cancer cells." (PMID 28465486, 2017). "Loss of RXRα either by genetic mutation or epigenetic regulation in mice underscores its importance in colon cancer development and makes it a vital nexus of control for incipient tumors to circumvent." (PMID 27167203, 2016). "For examples, targeted disruption of RXRα gene leads to skin abnormalities and prostatic preneoplastic lesions, while abnormal phosphorylation of RXRα is associated with the progresses of colon cancer and liver cancer." (PMID 26156677, 2015). "The association of LXRβ with the truncated form of RXRα (t-RXRα) was responsible for the sequestration of LXRβ in the cytoplasm in colon cancer cells." (PMID 26450852, 2015). "We found loss of RXRα protein in human colon cancers and cell lines." (PMID 27167203, 2016). "Specifically RXRα has been identified to be silenced by genetic mutations in human colon cancer and is associated with risk for colon adenoma, thus this inactivation, either by polymorphism or by silencing could be an important early event in carcinogenesis." (PMID 27167203, 2016). "Studies in our laboratory continue to identify whether silencing of RXRα and its implication for loss of regulation of inflammation are central to the development of colon cancer and it's potential as target for prevention." (PMID 27167203, 2016). "To further explore the possibility that EGCG could reverse RXRα loss of expression in human colon cancer, we tested the ability of EGCG to suppress proliferation in several human colon cancer cell lines, chosen for differences in their molecular phenotypes." (PMID 27167203, 2016). "In addition to colon cancer-associated mutations, PPARγ R280C and R288C found in uterine and skin cancers reduced the transcriptional activity of PPARγ and resulted in remarkably weak binding affinities for RXRα and MED1 co-activators." (PMID 33266062, 2020). "From a DNA methylation point of view, reduction in promoter methylation utilizing EGCG restores retinoid X receptor alpha (RXRα) expression in human colon cancer." (PMID 40969596, 2025). "TTC7B inhibited the proliferation of colon cancer cells by increasing the recruitment of RXRA to the FTO promoter, increasing FTO expression, and decreasing the total RNA m6A level." (PMID 39897037, 2025). "This suggests that EGCG can induce promoter demethylation, thereby reactivating the transcription of RXRα in colon cancer cells." (PMID 40969596, 2025). "We also analyzed the expression of nuclear receptors and showed that RXRα expression is decreased in U87-SphK2 cells, consistent with previous studies in colon cancer resistant to all-trans retinoic acid, the RXR agonist." (PMID 38280459, 2024). "Bigelovin, a sesquiterpene lactone isolated Inula hupehensis, binds specifically to RXRα-LBD with demonstrated anti-carcinogenic properties as observed in colon cancer cells." (PMID 35015251, 2022). "Evidence of RXRα involvement in relation to AP-1 inhibition was also shown in Caco2 human colon cancer cells." (PMID 32012980, 2020). "RXRα belongs to the steroid nuclear receptor super family and is downregulated in murine colitis, colorectal cancer, and colon cancer cell lines, although the exact mechanism is yet to be identified." (PMID 32422882, 2020). "Immunostaining also revealed predominant cytoplasmic RXRα staining in colon tumor from Tg-tRXRα mice." (PMID 30931933, 2019). "EGCG treatment decreased RXRα promoter methylation and consequently restored the expression of RXRα protein in human colon cancer cell lines, decreasing cell proliferation." (PMID 30627525, 2018). "This difference allowed us to study epigenetic status in relation to RXRα expression or its absence in the human colon cancer cells." (PMID 27167203, 2016).
colon carcinoma (continued). "Earlier, we reported that the nuclear transcription factor RXRα was epigenetically silenced in the AOM/ApcMin/+ mouse model for colon cancer, yet its expression was restored with a green tea intervention." (PMID 27167203, 2016). "Taken together, current research suggests that RXRα is a potential critical regulatory element in colon cancer." (PMID 27167203, 2016). "Methylation of the promoter of RXRα is one mechanism in which colon cancer tumors disable a key regulatory network." (PMID 27167203, 2016). "We previously found that colon tumors in ApcMin/+ mice had diminished levels of RXRα protein and expression levels of this gene were restored by treatment with a green tea intervention, due to reduced promoter methylation of RXRα." (PMID 27167203, 2016). "In colon cancer, RXRα, an important dimerization partner with other nuclear transcription factors, is silenced through this mechanism." (PMID 27167203, 2016). "Treatment of colon cancer cells with EGCG restored RXRα protein levels and reduced the amount of promoter methylation, revealing more evidence for EGCG as an epigenetic regulator in colon cancer chemoprevention." (PMID 27167203, 2016). "We demonstrated here that t-RXRα, the truncated form of RXRα (Retinoid X Receptor α), sequestrates LXRβ in the cytoplasm of colon cancer cells, thus potentiating the cytotoxic effects of agonist treatment." (PMID 26450852, 2015). "Here, we provide evidence that t-RXRα and, to a lesser extent RXRα, bind with LXRβ and dictate 1) its subcellular localization, 2) colon cancer cell sensitivity and 3) heathy cell resistance towards LXR agonist cytotoxicity." (PMID 26450852, 2015). "Apart from driving proteasomal degradation of β-catenin, RXRα also functions to suppress β-catenin-mediated upregulation of oncogenes through direct protein–protein interaction in colon cancer cells." (PMID 26500891, 2015). "Overall, these results suggest that t-RXRα can control the subcellular localization of LXRβ and thus T0901317-induced cell death of colon cancer cells." (PMID 26450852, 2015). "The activation of PPARγ/RXR heterodimer by their respective ligands synergistically inhibits cell growth, while inducing apoptosis in human colon cancer cells when the phosphorylation of RXRα was inhibited." (PMID 18528526, 2008). "TTC7B inhibits the proliferation of colon cancer cells in an RXRA-FTO axis-dependent manner." (PMID 39897037, 2025). "Furthermore, BBR can inhibit colon cancer cell growth by activating retinoid X receptor α (RXRα), which binds RXRα, and promoting β-catenin degradation." (PMID 32848804, 2020). "Here we show that SphK2 overexpression contributes to the resistance of all-trans retinoic acid (ATRA) therapy in colon cancer through rapid degradation of cytoplasmic retinoid X receptor α (RXRα) by lysine 48 (K48)- and lysine 63 (K63)-based polyubiquitination." (PMID 28465486, 2017). "With disruption of promoter methylation in RXRα and other genes involved in human colon cancers we wanted to determine if EGCG could induce demethylation of DNA by altering protein level and/or activity of methyltransferases." (PMID 27167203, 2016). "In CIMP+ human colon cancer cell lines we found RXRα promoter methylation is modulated by EGCG." (PMID 27167203, 2016). "In this study we establish that CIMP+ human colon cancer cell lines demonstrate reduced expression of the nuclear transcription factor RXRα and expression of this gene was restored using EGCG, a classic SMNP, which reduced the degree of promotor methylation in this gene." (PMID 27167203, 2016). "Moreover, we found that RARα, RXRα, and RXRβ showed higher expression, while RARβ showed lower expression in colon carcinoma cells (poorly differentiated), the normal colon (highly differentiated) being the control (data not shown)." (PMID 25881300, 2015).
colon carcinoma (continued). "In addition to APC, the β-catenin cellular level is also regulated through a direct proteasomal targeting mediated by RXRα and downregulation of RXRα in human and rodent colonic tumors has been reported previously." (PMID 26500891, 2015). "Berberine has also been shown to promote the interaction between retinoid X receptor alpha (RXRα) and nuclear β-catenin; this leads to the Casitas B-lineage lymphoma (c-Cbl)-mediated degradation of β-catenin, thereby inhibiting the proliferation of colon cancer cells." (PMID 33680978, 2020). "Moreover we showed that t-RXRα is mainly localized in the cytoplasm of colon cancer cells." (PMID 26450852, 2015). "In conclusion, our study demonstrated for the first time that TTC7B triggers the RXRA-FTO axis through PI4KA binding, which leads to a decrease in total RNA m6A modification and the inhibition of colon cancer progression." (PMID 39897037, 2025). "By overlaying genes found within this module with data from TCGA-COAD and CRC GWAS, we found that RXRA was one of 18 module members that was a target of CRC GWAS loci and was significantly reduced in colon tumors." (PMID 37509213, 2023). "Besides, by binging to retinoid X receptor alpha to suppress β-catenin signaling, BBR eventually inhibited the growth of colon cancer cells." (PMID 31319879, 2019). "CM from tRXRα-transfected but not from RXRα-transfected THP-1 cells enhanced STAT3 activation in human HCT-116 colon cancer cells." (PMID 30931933, 2019). "In accordance with this work, we also reported that t-RXRα was present in colon cancer samples but not in adjacent normal epithelial cells." (PMID 26450852, 2015). "Interestingly, as previously reported in all-trans retinoic acid-resistant colon cancer cells, SphK2 overexpression resulted in the downregulation of endogenous RXRα, but not of LXRα/β." (PMID 38280459, 2024). "In agreement with enhanced STAT3 activation, cell invasion assays showed that the invasion of colon cancer cells was significantly increased when they were cultured with CM from tRXRα-BMDMs or co-cultured with THP-1 cells expressing tRXRα but not RXRα." (PMID 30931933, 2019). "Likewise, we only found a statistically relevant correlation between colon cancer cell sensitivity to T0901317 and t-RXRα expression (p < 0.05) but not with RXRα expression (p > 0.05)." (PMID 26450852, 2015).